GRB7 (growth factor receptor bound protein 7)
Description:
Adapter protein that interacts with the cytoplasmic domain of numerous receptor kinases and modulates down-stream signaling. Promotes activation of down-stream protein kinases, including STAT3, AKT1, MAPK1 and/or MAPK3. Promotes activation of HRAS. Plays a role in signal transduction in response to EGF. Plays a role in the regulation of cell proliferation and cell migration. Plays a role in the assembly and stability of RNA stress granules. Binds to the 5'UTR of target mRNA molecules and represses translation of target mRNA species, when not phosphorylated. Phosphorylation impairs RNA binding and promotes stress granule disassembly during recovery after cellular stress (By similarity).
Tractability: Small molecule: a structure with a bound ligand is known; a high-quality ligand is known. Antibody: UniProt places it where antibodies can reach, with medium confidence; its Gene Ontology location is reachable by antibodies, with medium confidence; the Human Protein Atlas places it where antibodies can reach. PROTAC: a small molecule that binds it is known.
Gene: Protein-coding gene on chromosome 17 (39,737,490 to 39,747,292, forward strand). Ensembl gene ENSG00000141738.
Subcellular location: Cytoplasm; Cell junction, focal adhesion; Cell membrane; Cytoplasmic granule; Cell projection
Subcellular location (Human Protein Atlas): Cytosol; Plasma membrane
Pathways (Reactome):
Signal Transduction: Downstream signal transduction; GRB7 events in ERBB2 signaling; RND1 GTPase cycle; Signaling by SCF-KIT
Developmental Biology: RET signaling
Hemostasis: Tie2 Signaling
Gene Ontology:
Molecular function: identical protein binding; phosphatidylinositol binding; protein binding; protein kinase binding; protein-macromolecule adaptor activity
Biological process: positive regulation of cell migration; epidermal growth factor receptor signaling pathway; insulin receptor signaling pathway; intracellular signal transduction; negative regulation of insulin receptor signaling pathway; negative regulation of translation; stress granule assembly; signal transduction
Cellular component: cytoplasm; cytosol; focal adhesion; plasma membrane; cytoplasmic stress granule
Genetic constraint (gnomAD): Loss-of-function variants: 47 observed, 64.92 expected, observed/expected ratio (o/e) 0.72, 90% interval 0.57 to 0.92. The upper end of that interval is the gene's LOEUF score, 0.92, which puts it in group 3 of 6, group 1 being the genes least tolerant of losing a copy. Missense variants: 634 observed, 745 expected, observed/expected ratio (o/e) 0.85, 90% interval 0.8 to 0.91. Synonymous variants: 277 observed, 290.17 expected, observed/expected ratio (o/e) 0.95, 90% interval 0.87 to 1.05.
Homologues: Orthologues: chimpanzee GRB7 (100% identical), macaque GRB7 (99% identical), pig GRB7 (93% identical), rabbit GRB7 (92% identical), mouse Grb7 (91% identical), guinea pig GRB7 (90% identical), rat Grb7 (88% identical), dog GRB7 (88% identical), tropical clawed frog grb7 (66% identical), zebrafish grb7 (48% identical), Drosophila melanogaster pico (21% identical), Caenorhabditis elegans mig-10 (17% identical). Paralogues in human: GRB10 (53% identical), GRB14 (47% identical), RAPH1 (26% identical), APBB1IP (21% identical).
Diseases named in the same sentence as GRB7 in open-access papers:
GRB7 is named in the same sentence as 72 diseases in open-access papers, as found by Europe PMC text mining. Sharing a sentence is not in itself a finding about the gene and the disease. The quoted sentences say what the papers report.
breast carcinoma (78 papers, 2006 to 2025). "In this study low nuclear and cytoplasmic expression of GRB7 was significantly associated with good prognosis of breast cancer patients." (PMID 38036593, 2023). "Low nuclear and cytoplasmic expression of GRB7 was significantly associated with good prognosis of breast cancer patients (P = 0.012, P = 0.003 respectively)." (PMID 38036593, 2023). "In order to examine the biological significance of GRB7 membrane expression, we studied possible associations between cytoplasmic GRB7 protein expression with membrane accentuation with breast cancer risk factors." (PMID 32595827, 2020). "As with breast cancer, membrane expression of GRB7 protein is associated with a favorable prognosis." (PMID 32595827, 2020). "Although the consensus is that HER-2 positive breast cancer is generally associated with poor clinical outcome, we and others have found that GRB7 protein over-expression is a stronger independent adverse prognostic factor than HER-2 over-expression." (PMID 32595827, 2020). "High GRB7 expression is associated with decreased survival in patients with breast cancer, whereas overexpression of GRB7 and its variant (GRB7v) is correlated with high‐grade ovarian cancers." (PMID 32737994, 2020). "We find GRB7 membrane expression in both ovarian and breast cancers that are associated with high cytoplasmic expression of GRB7." (PMID 32595827, 2020). "GRB7 membrane expression is associated with less nodal involvement in breast cancer and a trend towards improved recurrence free survival in ovarian cancer." (PMID 32595827, 2020). "We have shown increased expression of VEGFA, which play a crucial role in the stimulation of angiogenesis via signaling through VEGF receptor 2, and GRB-7, which expression was shown to be strongly associated with decreased survival of breast cancer patients." (PMID 26759169, 2016). "The G7-18NATE peptide effectively inhibits the association between Grb7 and ErbB3, pancreatic cancer migration and breast cancer cell proliferation." (PMID 22253820, 2012). "Several studies have indicated that GRB7 had an adverse prognostic effect on breast cancer outcomes and is associated with up-regulation of GRB7 in breast cancer." (PMID 22140552, 2011). "Since ErbB2 has a role in proliferation of breast cancer cells and Grb7 associates with ErbB2, we are interested in looking at the effects of the Grb7 targeting peptide G7-18NATE-P on proliferation on a variety of different breast cancer cell lines." (PMID 17426702, 2007). "For example, GRB7 overexpression has been linked to increased tumor proliferation and migration in cervical and ovarian cancers and enhanced cell invasion in breast cancer and esophageal adenocarcinoma." (PMID 39360313, 2024). "Therefore, in this study we tested differences in ER, HER2 and GRB7 protein expression according to genetic ancestry, as well as the association of different combinations of expression of these proteins with breast cancer survival in Colombian women." (PMID 36620598, 2022). "Interestingly, on IHC analysis, we found that for HCC1954 and SKBR3 breast cancer cell lines there were varying degrees of GRB7 membrane-associated expression." (PMID 32595827, 2020). "Additionally, a shorter breast cancer-free interval has been linked to GRB7 overexpression." (PMID 39204147, 2024). "These aberrations highlighted well-known breast cancer-associated genes, such as MDM4, ZNF595, FGFR4, HIST1H1B, TPD52, DECR1, GRB7, and JUP55." (PMID 40162205, 2025). "In breast cancer, GRB7 was overexpressed and co-amplified with HER2, which promoted cell migration, invasion, and tumorigenesis." (PMID 39204147, 2024). "GRB7 is overexpressed in breast cancer cell lines, showing a strong correlation between mRNA levels and copy number status." (PMID 39720180, 2024). "HER2 and GRB7 were the two genes most observed in fusion events that were most frequently observed in glioblastoma, breast cancer, and ovarian cancer." (PMID 39204147, 2024).
breast carcinoma (continued). "Upregulation of GRB7 has been observed in breast cancer, bladder cancer, ovarian cancer, esophageal cancer, and GC." (PMID 39360313, 2024). "GRB7 is overexpressed in breast cancer cell lines and primary breast tumors along with HER2 protein." (PMID 37945744, 2023). "The significant associations observed between DARPP-32 and its downstream targets DKK1 and GRB7 and patient survival, underscore their importance in breast cancer." (PMID 38036593, 2023). "Here, considering its effect on HER2 and GRB7 expression, Her2-En1 is suggested as another potential target for dealing with breast cancer therapy." (PMID 37945744, 2023). "Growth factor receptor-bound protein 7 (Grb7) is an adaptor protein that is important in breast cancer cell migration and proliferation." (PMID 35625882, 2022). "Nowadays, few predictive markers were found for HER2+ BC patients with trastuzumab resistance, and our study was the first research to reveal that circCDYL2 and GRB7 were essential genes in regulating trastuzumab sensitivity of HER2+ breast cancer." (PMID 34980129, 2022). "Our previous study reported higher mRNA levels of the human epidermal growth factor receptor 2 (HER2)-amplicon genes ERBB2 and GRB7 in estrogen receptor (ER)-positive breast cancer patients with relatively high Indigenous American (IA) ancestry from Colombia." (PMID 36620598, 2022). "GRB7 has been found to have an important growth promoting function in human breast cancer cell lines, and inhibition of GRB7 will reduce the motility of breast cancer cells and promote cell death." (PMID 36686796, 2022). "We aimed to assess the association between genetic ancestry and the protein expression of ER, HER2, and GRB7, along with its clinical implications in Colombian patients with breast cancer." (PMID 36620598, 2022). "In terms of molecular expression level, GRB7 has been found to be overexpressed in a variety of human cancer tissues, including bladder cancer, breast cancer, ovarian cancer and hepatocellular carcinoma." (PMID 36686796, 2022). "We explored differences in the presentation of clinical-pathological features among breast cancer patients according to HER2/GRB7 status." (PMID 36620598, 2022). "Grb7 is identified as an independent prognostic marker in breast cancer and is identified as a potential target for the treatment of HER2+ve and TNBC tumours." (PMID 35625882, 2022). "Initially identified due to its co-overexpression with HER2, Grb7 has since been identified as an independent prognostic marker in breast cancer." (PMID 35625882, 2022). "Together, these results above suggest that circCDYL2 stabilizes GRB7 by inhibiting GRB7 ubiquitination, resulting in up-regulation of GRB7 protein in HER2+ breast cancer cells." (PMID 34980129, 2022). "In breast cancers, a high (3+) or a moderate (2+) level of GRB7 protein expression in the cytoplasm is present in 19.72% and 16.90% of breast cancers, respectively." (PMID 32595827, 2020). "This is in part due to the observation that only a percentage of breast cancer samples with GRB7 high expression have membrane expression." (PMID 32595827, 2020). "Membrane localization of GRB7 was present in a subset of breast cancers with high cytoplasmic GRB7 expression." (PMID 32595827, 2020). "GRB7 protein expression in the cytoplasm and membrane in fact, carries the opposite prognostic significance for breast cancer." (PMID 32595827, 2020). "GRB7 (growth factor receptor bound protein 7) was reported to play an important role in breast cancer progression." (PMID 32064261, 2020). "PE‐Lap (FBP1, ITGA11, TRIM68, BCAT1, ZNF780A, UTP20 and GRB7) predicted outcomes of breast cancer patients treated with lapatinib." (PMID 34766125, 2020). "Membrane expression of GRB7 protein was observed in breast cancer cell lines with high GRB7 protein expression in vitro." (PMID 32595827, 2020). "Membrane expression of GRB7 protein is observed in breast cancer cell lines with high GRB7 protein expression by IF and IHC." (PMID 32595827, 2020).
breast carcinoma (continued). "Clinically, high expression of both Grb7 and the ERBB family, especially ERBB2, are highly associated with a poor prognosis of patients with breast cancer." (PMID 31083325, 2019). "The tyrosine phosphorylation of EGFR was ablated in GRB7 knockdown ERBB2+ breast cancer, suggesting the effects of Grb7-mediated EGFR activation on the malignancy of ERBB2+ breast cancer." (PMID 31083325, 2019). "Overexpression of genes including post-GPI attachment to proteins 3 (PGAP3) and growth factor receptor-bound protein 7 (GRB7) are also associated with HER2 amplified breast cancers." (PMID 31083383, 2019). "Due to the identification of metastasis-acquired ERBB2 alterations in patients with breast cancer brain metastases, Grb7 has been recently indicated as one of the most recurrently upregulated genes in cancers." (PMID 31083325, 2019). "Actually, our study indicates that there are synergistic anti-cancer effects of cotreatment with Herceptin and shRNA targeting GRB7 in ERRB2+ breast cancers." (PMID 31083325, 2019). "In HER2+ breast cancer, Grb7 is co-overexpressed with HER2, leading to enhanced tumorigenesis and cell proliferation." (PMID 29018805, 2017). "While HER2 has a well-known role in breast cancer progression, overexpression of Grb7 has now also been identified as a significant predictor for reduced cancer-free periods and a worse prognosis for breast cancer patients." (PMID 29018805, 2017). "Remarkably, four well-described differentiating proteins in breast cancer subtypes, namely, Her2, Grb7, FOXA1 and MLPH, were clearly selected in the PAM50 as well as in the proteomic signatures." (PMID 26725330, 2016). "The MAP kinase adaptor proteins FRS2 and GRB7 were also highly amplified (10–20 copies in lung adenocarcinoma and breast cancer, respectively)." (PMID 24874471, 2014). "This suggests that GRB7 can be the focus for gene amplification and selective retention of the 17q11-12 segment and lends further evidence to the role of GRB7 protein over-expression as an independent adverse prognostic factor in breast cancer." (PMID 24102037, 2013). "Endogenous expression of the Grb7 protein and expression of the fusion protein of 41-mRLUC-3×Flag in SK-BR-3 breast cancer cells were first verified." (PMID 22253820, 2012). "For examples, the combination of Grb7 cyclic peptide, G7-18NATE, with chemo-drugs were capable of inhibiting breast cancer cell growth, or with the specific peptide ligand to suppress GRB7-mediated metastasis in pancreatic carcinoma etc." (PMID 23285101, 2012). "LUMB breast cancers are characterized by expression of HR along with HER2 associated genes (i.e., ERBB2 and GRB7) and a cell proliferation pattern designated by expression of MK167, CCNBI and MYBL2." (PMID 20492711, 2010). "Grb7 acts as a pro-survival factor in breast cancer cells as shown by the fact that RNAi-mediated removal of this protein reduces cell viability." (PMID 20126311, 2010). "Here, we focused on Grb7 because of its emerging relevance in breast cancer prognosis, and its supposed role in anticancer drug resistance." (PMID 20126311, 2010). "Co-amplification of ERBB2 and GRB7 was also found in human breast cancer cell lines, and has been additionally detected in non-invasive ductal carcinomas in situ." (PMID 19424485, 2008). "Increased expression of GRB7 correlates with a lower survival rate in breast cancer patients with tumors with either high or low expression of ERBB2." (PMID 19424485, 2008). "Analysis of chromosome 17q12 in a variety of different breast cancer cell lines Grb7 was found to have a high DNA copy number with a high level of ErbB2 co-expression." (PMID 17426702, 2007). "Grb7 is tightly co-amplified with the ErbB2 receptor in breast cancer cell lines and there is a strong correlation between ErbB2 and Grb7 over-expression in primary breast cancer specimens, as well as in oesophageal and gastric carcinoma." (PMID 17894853, 2007).
breast carcinoma (continued). "We found significant inhibition of proliferation on SK-BR-3 breast cancer cells treated with the Grb7 targeting peptide, G7-18NATE-P." (PMID 17426702, 2007). "These interactions may underlie the observed inhibition of breast cancer cell proliferation and decrease in cell migration of pancreatic cancer cells treated with G7-18NATE, making it of considerable importance to further characterise this peptide and its interactions with Grb7 SH2 domain." (PMID 17894853, 2007). "This series of experiments demonstrates that the Grb7 targeting peptide cooperatively inhibits the proliferation of SK-BR-3 breast cancer cells with Doxorubicin and Herceptin." (PMID 17426702, 2007). "HER2 and GRB7 have been shown to be co-amplified in breast cancer, and previous studies have suggested that this co-amplification may impact the prognostic value of HER2 status alone." (PMID 39506855, 2024). "Additionally, in breast cancer, circCDYL2 forms a complex with GRB7 and FAK, sustaining downstream signaling pathways of HER2 and contributing to trastuzumab resistance." (PMID 38654320, 2024). "Thus, GRB7 overexpression plays an essential role in activating signal transduction and tumor growth in breast cancer cells by amplification of chromosome 17q11-2123." (PMID 37945744, 2023). "We previously identified DKK1 and GRB7 as genes with linked expression using Artificial Neural Network (ANN) analysis; here, we determine protein expression in a large cohort of early-stage breast cancer patients." (PMID 38036593, 2023). "GRB7 expression was determined in a cohort of early-stage breast cancer patients." (PMID 38036593, 2023). "Furthermore, we found that the expression of GRB7 protein displayed a positive correlation with circCDYL2 in HER2+ breast cancer patient tissues who treated with anti-HER2 therapy (R = 0.65, P < 0.001)." (PMID 34980129, 2022). "It was identified that silencing of miR-193a-3p through hypermethylation can promote HER2 positive breast cancer progress by targeting growth factor receptor bound protein 7 (GRB7), extracellular signal-regulated kinase 1/2 (ERK1/2), and forkhead box M1 (FOXM1) signaling." (PMID 33628829, 2021). "Furthermore, GRB7 has been characterised as a promising therapeutic target in breast cancer treatment, primarily in combination with either doxorubicin or trastuzumab." (PMID 32737994, 2020). "Though frequently amplified and over-expressed concurrently with HER-2 in breast cancers with chromosome 17q11-12 amplification, we and others have shown that GRB7 expression is an independent adverse prognostic factor for breast cancer, including the triple negative breast cancer subtype." (PMID 32595827, 2020). "Moreover, the ERBB2/Grb7-mediated Shc/Ras signal transduction cascade has been reported to regulate the proliferation of ERBB2-overexpressing breast cancers." (PMID 31083325, 2019). "Of note, our study indicates that the anti-cancer effect is synergized by cotreatment with Herceptin, an ERBB2-targeted monoclonal antibody, plus Grb7 knockdown in ERBB2+ breast cancers, reflecting the tight correlation between Grb7 and ERBB2 in cancer progression and treatment." (PMID 31083325, 2019). "Moreover, the study also indicated that the GRB7 gene is clearly different between her2-positive breast cancer and other breast cancer subtypes." (PMID 30866472, 2019). "Additionally, the elevated expression of Grb7 was highly correlated with late clinical stage or low survival in patients with cancers, including breast cancers and esophageal carcinoma." (PMID 31083325, 2019). "The ERBB2, GRB7 and MIEN1 genes, which are located on chromosome 17 in relative proximity within a region including approximately 60,000 base pairs, have been reported co-amplified and associated with poor prognosis in breast cancer." (PMID 28832682, 2017). "Further, GRB7 amplification may be a drug resistance mechanism during anti-Her-2 therapy, such as lapatinib treatment in breast cancers." (PMID 24874471, 2014).